HMGB1 (high mobility group box 1)
Diseases named in the same sentence as HMGB1 in open-access papers (continued):
Sharing a sentence is not in itself a finding about the gene and the disease.
tumor (continued). "Immunofluorescence staining revealed that Cu-DON could induce a strong ICD response in tumor cells, as evidenced by effective calmodulin (CRT) exposure and high mobility group box 1 (HMGB1) release of 4T1 cells after Cu-DON treatment, which are pivotal biomarkers of ICD." (PMID 34983555, 2022). "HMGB1 expression did not significantly differ between tumor and normal tissues." (PMID 36324584, 2022). "TANs impair antitumor immunity and accelerate tumor growth and metastasis through the production of growth factors, chemokines, and inflammatory factors such as matrix metalloproteinase-9 (MMP-9), vascular endothelial growth factor (VEGF), high mobility group box 1 (HMGB1), and interleukin (IL)-17." (PMID 36060811, 2022). "Thus, ILC2s could potentially respond to HMGB1 via RAGE or its other receptors in premalignant and malignant lesions, however, if and what effect this has on tumor development is currently unknown." (PMID 36032129, 2022). "Finally, co-injection of B cells and CM with HMGB1-overexpressing tumor cells, but not with glycyrrhizin, significantly enhanced tumor growth associated with increased microvascular density in ESCC xenograft mice model." (PMID 34617194, 2022). "Similar to the present results, their experiments showed that knockdown of HMGB1 in tumor cells did not affect the in vitro tumor growth, but in vivo tumor progression was suppressed by the knockdown and longer overall survival was observed in knockdown tumor animals." (PMID 35150340, 2022). "Notably, blood HMGB1 levels in the BNCT group on day 8 remained two-fold higher than those on day 3, indicating that the BNCT-induced increase in blood HMGB1 levels can be detected when tumor regression continues." (PMID 35336794, 2022). "However, the deletion or mutation of HMGB1 leads to the low expression of MHC class I (MHC-I), which fails to present tumor-derived antigens to CD8+ T cells, resulting in the failure of cytotoxic T cells to effectively recognize and kill tumor cells." (PMID 36230798, 2022). "Moreover, the addition of EI-NP enhanced the pyroptosis as evidenced by the increased generation of tumor antigen HMGB1 but did not alter the expression of cleaved caspase 1 or cleaved GSDMD." (PMID 36280674, 2022). "DAMPs, such as nuclear high-mobility group box 1 (HMGB1) and mitochondrial DNA (mtDNA), are released by hypoxia-induced intracellular translocation and couple together to form a complex that stimulates TLR9 signaling pathways to facilitate tumor cell proliferation." (PMID 36233088, 2022). "Tumor cells can release HMGB1 into the local microenvironment, where HMGB1 interacts with several receptors, such as toll-like receptor 2 (TLR-2), TLR-4, TLR-9, and the receptor for advanced glycation end products (RAGE), which can lead to tumor cell survival, proliferation, and angiogenesis." (PMID 34617194, 2022). "Although ethylpyruvate and glycyrrhizin are not specific inhibitors for HMGB1, it is an open question whether these inhibitors effectively decrease the tumor cell proliferation after BNCT irradiation by inhibiting HMGB1 function." (PMID 35336794, 2022). "Notably, HMGB1 may also favor endothelial progenitor cell homing and increase their neovascularization capacity in a RAGE/TLR4-dependent manner, thus promoting tumor angiogenesis." (PMID 35727208, 2022). "Moreover, we also measured the HMGB1 basal levels in mice without tumor xenografts, using a different ELISA kit, 3 days after whole-body neutron irradiation following BPA administration at 500 mg/kg bodyweight." (PMID 35336794, 2022). "The location of HMGB1 in the cytoplasm or extracellular space will promote the release of cytokines such as IL-6 and IL-8 by activating MAPK- and MyD88-dependent NF-KB pathways, thereby prompting tumor cell proliferation, angiogenesis, EMT, invasion, and metastasis." (PMID 35273678, 2022).
tumor (continued). "Given that MP9 and its conjugates induced ICD by releasing DAMPs like HMGB1, ATP and CRT, the potential of the PEG-MP9-aPDL1 peptide-polymer conjugate to induce a tumor immunotherapeutic response in vivo was investigated following systemic administration in CT26 tumor bearing female BALB/c mice." (PMID 35547769, 2022). "In addition to its role in tumor proliferation, HMGB1 plays a nonnegligible role in tumor metastasis." (PMID 36384979, 2022). "Additionally, some IRGs with copy number amplification (HMGB1, IL17RA, and BAX) showed increased expression in tumor tissues, while some IRGs with copy number deletions (IL10, NT5E, and ENTPD1) showed decreased expression in tumor tissues." (PMID 36386817, 2022). "Importantly tumor cell-derived HMGB1 may also act on RAGE in the TAMs to promote NF-κB-dependent PD-1 expression given the spatial proximity between TAMs and their host tumor cells in the tumor tissues." (PMID 34488792, 2021). "Importantly, in the supernatant of SCC VII and 4T1 tumor cells, we only detected large amounts of uric acid, whereas HMGB1 levels were low and S100A8/9 was not present (not shown)." (PMID 34876407, 2021). "Indeed, both HMGB1 and CXCL12 promote tumor cell growth, survival, and invasion." (PMID 33956406, 2021). "In cancers, studies have reported that tumor-derived factors such as granulocyte-macrophage colony-stimulating factor (GM-CSF), interleukin 6 (IL-6), long non-coding RNA HOXA transcript at the distal tip (HOTTIP) and high-mobility group box-1 (HMGB1) can induce PD-L1 expression on neutrophils." (PMID 34519637, 2021). "Moreover, the translocation pattern was categorized using “site-index”, and the results demonstrated that the overexpression of HMGB1 and SOX9 was mostly observed in both the nucleus and cytoplasm, whereas YAP1 was predominantly expressed in the cytoplasm of tumor cells." (PMID 35201494, 2021). "A previous study in our laboratory also revealed that HMGB1 from dying tumor cells stimulated the proliferation of living tumor cells and presaged poor prognosis in cancer patients, but did not examine the effect of HMGB1 on neosis and tumor repopulation after radiotherapy." (PMID 33523579, 2021). "ICD involves the cell surface exposure of calreticulin (CRT), release of DAMPs-related high mobility group box1 (HMGB1) and autophagy-dependent ATP release, which together, leads to the antigen uptake and presentation of DC cell, and then activates the CD8+ TILs to play the anti-tumor role." (PMID 34283088, 2021). "Interestingly, pretherapeutic levels of HMGB1 and other tumor markers were not predictive for therapy response in NSCLC patients." (PMID 33672622, 2021). "Moreover, the interaction of HMGB1 and TIM3 on DC interferes with nucleic acid recruitment to endosomal compartments impairing the innate immune sensing of nucleic acids released by dying tumor cells." (PMID 33418996, 2021). "Moreover, correlation analysis revealed that HMGB1 cytoplasm-staining score and HMGB1 total score were related to tumor grade (p = 0.0049, r = 0.2863; p = 0.0005, r = 0.3508; respectively), whereas HMGB1 nucleus-staining score was not related (data not shown)." (PMID 34257571, 2021). "HMGB1 activates RAGE or activates the peroxisome via the proliferator-activated receptor gamma (PPAR-γ) with consequent inhibition of the HMGB1-RAGE axis, and this mechanism could also represent a future therapeutic strategy beneficial against tumours." (PMID 34445745, 2021). "While, in our study, we could hardly find HMGB1 in Lewis lung cancer-derived exosomes, another classic cachexia model (data not shown), which may indicate that different tumor types have different cachexins." (PMID 34867338, 2021).
tumor (continued). "HMGB1 released from dying tumor cells rather than intracellular HMGB1 could promote neosis‐based tumor repopulation." (PMID 33523579, 2021). "However, the effects of CD26/DPP4-mediated HMGB1 processing on its anti-bacterial and anti-tumor effects and its regulated release have not been analyzed so far." (PMID 34885056, 2021). "In malignant cells lacking TLR4, the same effect could be triggered by HMGB1 indirectly through TLR4-expressing myeloid cells present in the tumour microenvironment (e." (PMID 34234778, 2021). "Fibulin-3 and HMGB1 were highly expressed in tumor tissue rather than adjacent tissue." (PMID 33230247, 2020). "We also found that PD-L1 upregulation was not totally inhibited by blocking the HMGB1 pathway, suggesting that there may exist other suppressive pathways mediated by tumor-derived EVs." (PMID 32477934, 2020). "Although our in vitro findings demonstrated that DOC induced all DAMPs in 3LL cells, HMGB1 secretion was significantly lower in DOC-treated or OXA-treated cells compared to all other treatments, which might explain why these mice developed a tumor after all." (PMID 32560232, 2020). "Moreover, hypoxia did not cause the death of tumor cells, either 4T1 or EMT6, indicating that HMGB1 is the product of cell secretion rather than cell lysis." (PMID 32943604, 2020). "Since HMGB1 is not the only factor that affects the survival and function of MDSCs, additional research is needed to accurately understand the interaction between the transition of tumor MDSCs and their inhibitory activity." (PMID 32551121, 2020). "Similarly, levels of ds-HmgB1 are high in the tumor microenvironment, at the same time it is absent in cachectic muscles from the same tumor bearing mice." (PMID 33114717, 2020). "Additionally, in a murine xenograft model of A549, DHA-37 could inhibit tumor growth, and increase p-ERK, p-P38, HMGB1, and LC3 in tumor tissue, which is consistent with in vitro data." (PMID 32733246, 2020). "Furthermore, HMGB1 release also confirmed that free OLE and PEG-TECM-NS/OLE could efficiently induce immunogenicity of the tumour cells." (PMID 33009382, 2020). "Still, targeting HMGB1 or histone-deacetylase 11 by specific inhibitors could also provide an avenue to inhibit MDSC expansion and limit IL-10 production and thus enhance anti-tumour/infection immune responses." (PMID 32931721, 2020). "Moreover, HMGB1 can increase the release of CXCL12 from stromal cells and induce the aggregation of a large number of neutrophils and dendritic cells (DCs) at the tumor site, thereby eliminating infiltrating tumor cells." (PMID 32551121, 2020). "The activation of TLR2 on tumor infiltrating myeloid or Treg cells is induced directly by cancer cells, which are able to secrete TLR2 endogenous ligands, such as the chondroitin sulfate proteoglycan versican, HMGB1 (which will be discussed in the following paragraphs) and Wnt5a." (PMID 33321934, 2020). "HMGB1 was found to be critical for β-lap-induced immunogenicity in three experiments: (i) BMDCs were exposed to OVA protein for 4 h, then naïve OT1 CD8+ T cells and the supernatants from β-lap-treated tumor cells (with/without αHMGB1 antibody or knockdown the HMGB1 in MC38 cells)." (PMID 31324798, 2019). "Our results demonstrate that DOC induces CD8+ T cell recruitment to the tumor microenvironment by enhancing the secretion of HMGB1 and CXCL11, thus improving the anti-tumor efficacy, indicating that modulating the HMGB1-CXCL11 axis might be helpful for NSCLC treatment." (PMID 30744691, 2019). "In the context of chemoresistance, HMGB1 is detrimental because it prevents cells from dying (inhibiting apoptosis and promoting autophagy) whereas in ICD, HMGB1-induced autophagy is considered an immunogenic signal that will ultimately lead to tumor elimination." (PMID 31379812, 2019).
tumor (continued). "Moreover, combining radiation and HMGB1 inhibition significantly impaired tumor infiltrating MDSCs and TAMs -but not Tregs- and shifted the overall tumor immune balance towards anti-tumoral response." (PMID 31015520, 2019). "Interestingly, HMGB1 is overexpressed in several cancers, including the human breast cancer cell line MCF-7, in which its silencing provoked significantly higher levels of tumor cell apoptosis and lower levels of migration and invasion in in vitro assays." (PMID 31852512, 2019). "Indeed, we observed a dose-dependent secretion of HMGB1 in NQO1+ tumor cells but not in NQO1− cells." (PMID 31324798, 2019). "Therefore inhibition of the HMGB1–RAGE interaction might be a promising therapeutic approach for the modulation of the inflammatory and tumor-facilitating activity of HMGB1." (PMID 30123419, 2018). "Necrotic cells release their cellular cytoplasmic contents into the extracellular space, such as high mobility group box 1 (HMGB1), which is a nonhistone nuclear protein, but acts as a proinflammatory and tumor-promoting cytokine when released by necrotic cells." (PMID 29636841, 2018). "Finally, it is of great interest to define biomarkers able to predict clinical response to chemotherapy in BC patients, in this regard candidate biomarkers are tumor infiltration by CD8+ T cells and TFH and in situ expression of markers such as HMGB-1 and autophagy." (PMID 29334915, 2018). "Thus, caution must be exercised because of the potential positive and negative aspects of HMGB1 expression during different phases of tumor development and treatment." (PMID 30258050, 2018). "HMGB1 levels were consistent and largely independent of the actual tumor load or treatment regimen." (PMID 30123419, 2018). "Our data demonstrated that the effect of HMGB1 on MDSC was dose dependent, and only high dose of HMGB1 could inhibit the differentiation and proliferation of MDSCs and mobilize the body's immune activity to kill tumor." (PMID 28968989, 2017). "Nevertheless, it is not known whether miR-200c acts as a tumour suppressor through downregulating HMGB1 in NSCLC." (PMID 28727734, 2017). "However, the current knowledge concerning the positive and negative effects of HMGB1 on tumor development is not explicit." (PMID 28969092, 2017). "Thus, our findings indicated that HMGB1 might mediate tumor immune escape by promoting MDSCs cell proliferation, which provided a novel theoretical basis for preventing RCC using HMGB1 as the target." (PMID 28968989, 2017). "After intravasation, most of tumor cells in circulation are damaged by the shear stress and mechanical stresses in blood, thus releasing intracellular molecules, many of which have been identified as the ligands for TLR2/4, including HMGB1, HSP60, HSP70, gp96, S100A8, S100A9, SAA3 and so on." (PMID 28415700, 2017). "To further investigate the tumour-promoting effects of HMGB1 release, as a consequence of tumour hypoxia and given the absence of evidence for a direct effect of HMGB1 on tumour cell growth or apoptosis in vitro, we analysed the immune cell infiltrate within the tumour microenvironment." (PMID 27426915, 2016). "The definition of whether and how NK cells are recruited, migrate within the tumor, and influence the EMT, along with the new insights into the putative role of HMGB1, would provide new important elements to maximize the still unexplored potential of NK cells in the therapy of solid tumors." (PMID 27294158, 2016). "ICD results in the release of tumor antigens and “danger signals,” also known as damage-associated molecular patterns (DAMPS), such as calreticulin, ATP, type I IFN, and non-histone chromatin-binding protein high-mobility group box 1 (HMGB1)." (PMID 27847783, 2016). "In current meta-analysis, we revealed that HMGB1 overexpression was significantly associated with a poorer OS and a shorter PFS in cancer patients, moreover, the statistical significance was constant irrespective of different tumor types." (PMID 27391431, 2016).
tumor (continued). "We propose that similar to in vitro data, in vivo GemOE cells recruit MSCs to their vicinity through secreting Ac-HMGB1 that promotes expression and activation of RAGE, which in turn induces CXCR4 expression in MSCs that responds to high levels of SDF1 secreted from GemOE tumor cells." (PMID 26989079, 2016). "Similar to mice in which tumour expression of HMGB1 was silenced or inhibited with recombinant BoxA, mice treated with anti-IL-10 exhibited significantly delayed tumour growth compared to controls, whereas anti-IL-10 did not significantly affect the growth of HMGB1-shRNA-transduced B16 tumours." (PMID 27426915, 2016). "We also showed that HMGB1 passively diffused out of dying necrotic cells in the cores is also acetylated and thus could also be involved in the directed migration of MSCs towards SDF1 secreting GemOE tumor cells within the cores." (PMID 26989079, 2016). "HMGB1 is a key mediator of chronic inflammation in MM, leading to Nalp3 inflammasome activation, macrophages accumulation, interleukin (IL)-1β and TNF-α secretion, and thus to activation of the NF-κB pathway, which increases cell survival and tumor growth after asbestos exposure." (PMID 27171110, 2016). "Release of the alarmin molecule HMGB1 into the extracellular matrix activates toll-like receptors and stimulates dendritic cell antigen presentation and IL1β production, leading to CD8 T cell activation, while ATP released from apoptotic tumor cells can activate dendritic cells." (PMID 27515027, 2016). "However, HMGB1 is also released extracellularly during ‘immunogenic’ cell death, and functions in conjunction with other DAMP molecules to induce autophagy in neighboring tumor cells." (PMID 27917193, 2016). "The overall strong therapeutic effect may be due to the release of tumor-specific antigens released into the extracellular compartment, together with potent immune stimulatory molecules (DAMPS) such as ATP, cytochrome-C and HMGB1." (PMID 26472184, 2015). "Compared to patients with low HMGB1 expression, those with high expression had a poorer response to CRT, in terms of tumor reduction ratio (42.2 versus 28.9%, respectively; P <0.01) and post-CRT histological tumor regression grade (56.5 versus 30.8% grade 2; respectively; P = 0.03)." (PMID 25622595, 2015). "Concerning therapy response, however, baseline HMGB1 levels in patients with no response to therapy were higher and sRAGE levels were lower than in patients with histological partial or complete remission at tumor surgery." (PMID 26854151, 2015). "The role of inflammasomes in carcinogenesis is contrasting; they may inhibit tumor promotion by activating caspase-1 and cell killing, or may promote tumor growth by upregulating secretion of pro-inflammatory molecules like, IL-1β, IL-18, FGF2 and HMGB1." (PMID 26689911, 2015). "HMGB1 not only increased cyclin D1 and PCNA to induce the proliferation of HCC, but also regulates for tumor multiplicity and size, alpha-fetoprotein (AFP) level and advanced TNM stage in HCC, indicating HMGB1 could be used as a biomarker for HCC diagnosis which deserves further study." (PMID 26393575, 2015). "Also as pro-angiogenic inducer, the role of HMGB1 in different redox states has never been defined in tumour angiogenesis." (PMID 26099505, 2015). "However, it is possible that a cross-talk between HMGB1/TNF-α and HGF/Met/Akt may occur in MM also, supporting and reinforcing the process of MM carcinogenesis and tumor progression." (PMID 28548074, 2014). "Thus caution must be exercised, given the potential positive and negative aspects of HMGB1 expression at different phases of tumor development and during treatment." (PMID 25512109, 2014). "Thus, CpG island hypermethylation induced silencing of HMGB1 and possibly other HMGB genes, may compromise the immune system, promoting tumor development and progression." (PMID 24479488, 2014).